TET2 (tet methylcytosine dioxygenase 2)
Diseases named in the same sentence as TET2 in open-access papers (continued):
Sharing a sentence is not in itself a finding about the gene and the disease.
coronary atherosclerosis (1 paper, 2019). Atherosclerosis of the coronary vasculature. "But in our studies, we surprisingly found the levels of 5-mC and 5-hmC and TET2 expression elevated with the increase of the severity of coronary atherosclerosis, while DNMTs expression had no significant change." (PMID 31123222, 2019).
cutaneous T-cell lymphomas (1 paper, 2023). "Although both cell lines (HuT78 and HH) derived from CD4+ cutaneous T-cell lymphomas are probably similar to normal CD4+ T cells, they lack mutations in TET2, DNMT3A, and IDH2 in contrast with the neoplastic cells of AITL." (PMID 37370838, 2023).
diabetic nephropathy (1 paper, 2021). "Additionally, the level of Tet2 is significantly increased in diabetic wounds, and Tet2 is associated with insulin sensitivity and the pathogenesis of diabetic nephropathy." (PMID 34222235, 2021).
diabetic polyneuropathy (1 paper, 2023). "They suggested that the conflicting action of DNMT3A and TET2 in DNA methylation and hematopoietic stem cell differentiation might explain their opposite association with diabetic polyneuropathy." (PMID 36807865, 2023).
ductal carcinoma in situ (1 paper, 2021). "Moreover, during the progression from ductal carcinoma in situ (DCIS) to invasive ductal carcinoma (IDC) in breast cancer, the nuclear expression of TET1 and TET2 decreased significantly, accompanied by a reduction in global DNA 5hmC level." (PMID 33716151, 2021).
dysplasia (1 paper, 2025). A usually neoplastic transformation of the cell, associated with altered architectural tissue patterns. "CHIP is currently defined by the presence of somatic mutations commonly seen in hematologic malignancies (e.g., DNMT3A, TET2, ASXL1) in individuals without cytopenia or dysplasia." (PMID 41464583, 2025).
E. coli infection (1 paper, 2021). "Collectively, these data suggest that Tet2 is involved in the regulation of macrophage functions triggered by LPS and during E. coli infection." (PMID 35011643, 2021).
EBV infection (1 paper, 2016). "This also indicated that TET2 functions as a resistance factor against DNA methylation during EBV infection, and TET2 depletion leads to a loss of protective mechanisms and the acquisition of de novo methylation." (PMID 27829228, 2016). "Hydroxymethylation target genes induced by TET2 were significantly overlapped with methylation target genes during EBV infection." (PMID 27829228, 2016). "Immunoblotting analyses also showed that TET2 protein expression was significantly repressed by EBV infection in both MKN7 and GES1 cells." (PMID 27829228, 2016). "When TET2 was knocked down, more genes acquired de novo methylation by EBV infection, including genes that were resistant to de novo methylation around TSS in shNON_EBV cells." (PMID 27829228, 2016). "TET2 was downregulated during EBV infection, and this was at least partially caused by expression of EBV transcripts, BARF0 and LMP2A, and upregulation of human miRNAs targeting TET2." (PMID 27829228, 2016). "Downregulated genes in response to EBV infection included TET1 and TET2, which encode TET family demethylation enzymes." (PMID 27829228, 2016). "TET2 was markedly downregulated after EBV infection, and TET1 was expressed at low levels in both cells." (PMID 27829228, 2016). "We conducted an RNA-seq analysis of gastric epithelial cells with and without EBV infection and found that TET family genes, especially TET2, were repressed by EBV infection at both mRNA and protein levels." (PMID 27829228, 2016). "We here show an important role of TET2 as a resistance factor against de novo methylation during EBV infection and the contribution of TET2 downregulation to DNA methylation acquisition." (PMID 27829228, 2016). "When TET2 was knocked down by shRNA, EBV infection induced de novo methylation more severely, including even higher methylation in methylation-acquired promoters or de novo methylation acquisition in methylation-protected promoters, leading to gene repression." (PMID 27829228, 2016). "If TET2 is a resistance factor for methylation acquisition, the knockdown of TET2 might accelerate methylation acquisition during EBV infection." (PMID 27829228, 2016). "Since TET2 expression was markedly decreased after EBV infection in both MKN7 and GES1 cells among the three TET family genes, and TET2 is involved in cytosine hydroxymethylation, we hypothesized that TET2 downregulation contributes to methylation, at least partially." (PMID 27829228, 2016). "In summary, we found that TET2 is downregulated during EBV infection via expression of EBV transcripts and upregulation of human miRNAs targeting TET2, and that TET2 may function as a resistance factor against DNA methylation in gastric epithelial cells." (PMID 27829228, 2016). "While TET2 depletion itself does not increase the methylation level, the downregulation of TET2 contributes to methylation induction by EBV infection." (PMID 27829228, 2016). "TET2 knockdown alone without EBV infection did not induce de novo DNA methylation." (PMID 27829228, 2016).
embryonic carcinoma (1 paper, 2014). "We depleted TET1, TET2, and TET3 in a pluripotent embryonic carcinoma cell model and examined the impact on genome-wide 5mC, 5hmC, and transcriptional patterns." (PMID 24958354, 2014).
endometrial adenocarcinoma (1 paper, 2022). "Multivariate Cox regression analysis showed that TET2 expression was an independent risk factor for prognosis in patients with endometrial adenocarcinoma (HR = 14.520, 95% CI was 1.From 060 to 198.843, P = 0.045)." (PMID 35480097, 2022). "TET2 expression in endometrial adenocarcinoma was correlated with the degree of differentiation (P < 0.05)." (PMID 35480097, 2022). "We also compared TET2 expression between different histopathological samples (Endometrioid endometrial adenocarcinoma, Serous endometrial adenocarcinoma, Mixed serous and endometrioid)." (PMID 35480097, 2022). "Immunohistochemical analysis showed that TET2 and 5hmC levels were significantly lower in endometrial adenocarcinoma(P<0.05)." (PMID 35480097, 2022). "Multivariate COX regression analysis revealed that TET2 might serve as an independent prognostic factor in patients with endometrial adenocarcinoma, and may be useful in predicting therapeutic effects." (PMID 35480097, 2022).
Fanconi anemia (1 paper, 2018). Fanconi anemia (FA) is a hereditary DNA repair disorder characterized by progressive pancytopenia with bone marrow failure, variable congenital malformations and predisposition to develop hematological or solid tumors. "WES revealed that HMCLs displayed frequent mutations in Fanconi anemia genes (PALB2 [12%], FANCI [12%], FANCA [9%], FANCD2 [9%], BRCA2 [9%]) as well as in helicases (such as RECQL4, 15%, and BLM, 15%) and epigenetic modifiers (e.g., TET2, 15% and SETD2, 6%)." (PMID 30545397, 2018).
fibroepithelial polyp (1 paper, 2025). A polypoid lesion composed of fibrous tissue and epithelium. "The other mutations found in our case (DNMT3A, C8B, TET2, SDHA, ARID1B, NOTCH1, OR5L1, and KDM6A) do not have a known association with the formation of fibroepithelial polyps." (PMID 40936011, 2025).
gastric MALT lymphomas (1 paper, 2021). "The frequency of TNFAIP3, TET2, and NOTCH1 mutations in H. pylori negative gastric MALT lymphoma is similar to those seen in unselected gastric MALT lymphomas, whereas the previously reported TNFRSF14 alterations affecting gastric MALT lymphomas were absent in the current series." (PMID 34203889, 2021).
gestational diabetes mellitus (1 paper, 2019). "Significant changes of TET2 expression and 5hmC abundance have been found in the umbilical veins of gestational diabetes mellitus (GDM) pregnancies." (PMID 30987683, 2019).
Granuloma (1 paper, 2020). A compact, organized collection of mature mononuclear phagocytes, which may be but is not necessarily accompanied by accessory features such as necrosis. "TET3 correlated positively with TET2, DNMT1, and negatively correlated with granulomas number and miR31-3p and 122-3p expression." (PMID 32078636, 2020).
hypercoagulability (1 paper, 2025). "CHIP is characterized by the expansion of hematopoietic stem cell clones harboring somatic mutations in genes such as TET2, DNMT3A, and ASXL1, which are implicated in inflammation, atrial remodeling, and hypercoagulability." (PMID 40141381, 2025). "In addition to JAK2, mutations in TET2 and DNMT3A play critical roles in CHIP-mediated hypercoagulability." (PMID 40141381, 2025).
hypertrophic cardiomyopathy (1 paper, 2023). A condition in which the myocardium is hypertrophied without an obvious cause. "A total of 433 DEGs representing known pathways for calcium signaling, PI3K/AKT signaling, RAS signaling, MAPK signaling, PPAR signaling, insulin secretion, and dilated and hypertrophic cardiomyopathy signaling were upregulated in Ob/Ob mice bearing Tet2–/– cells compared with WT recipient mice." (PMID 37071471, 2023).
infarct (1 paper, 2023). "In contrast, a study from 2022 with n = 150 patients with AMI showed a significant increase in Tet-2 levels, positive correlation of Tet2 with infarct size, cTNT levels and Gensini score (all, p < 0.001)." (PMID 37762023, 2023).
Intellectual disability (1 paper, 2019). "Through Northern Finland Intellectual Disability (NFID) Cohort, we could identify a carrier of de novo nonsense mutation in TET2 (NM_001127208.2:c.1471C>T, NP_001120680.1:p.Gln491Ter; hereafter individual Id1 with TET2X mutation)." (PMID 30890702, 2019).
Intervertebral Disc Degeneration (1 paper, 2025). "β‐Mangostin alleviates intervertebral disc degeneration through dual modulation of macrophage polarization and the TET2‐Prkcg axis in nucleus pulposus cells." (PMID 40558107, 2025).
intrahepatic cholangiocarcinoma (1 paper, 2022). A carcinoma that arises from the intrahepatic bile duct epithelium in any site of the intrahepatic biliary tree. "Although intrahepatic cholangiocarcinoma (iCCA) may harbour IDH1/2 mutations, the contribution of TET2 to carcinogenesis remains unknown." (PMID 34905094, 2022).
iron overload (1 paper, 2020). "The higher incidence of ASXL1 and TET2 gene mutations in our iron overload (IO) MDS patients suggests that IO may be involved in the pathogenesis of MDS." (PMID 33178287, 2020).
ischemic disease (1 paper, 2023). Lack of blood supply to an area of the body, resulting in impairment of tissue oxygenation. "Taken together, these data suggest that TET2 is closely associated with angiogenesis in ischemic diseases." (PMID 36658614, 2023). "According to the present results, TET2 was a master DNA demethylase that regulated angiogenesis and post‐ischemic, thus providing evidence for the potential therapeutic role of targeting TET2 in the treatment of ischemic diseases." (PMID 36658614, 2023). "Overall, this study provided deeper insights into the regulation of 5-hmC level in ECs function and presented a new effective strategy that the TET2-5-hmC pathway may be a potential treatment for ischemic disease." (PMID 36658614, 2023). "Collectively, we revealed the potential implication of TET2 in the treatment of ischemic disease." (PMID 36658614, 2023).
lentivirus infection (1 paper, 2024). Virus diseases caused by the Lentivirus genus. "The regulatory and functional roles of DNMT3a and TET2 were studied by lentivirus infection and puromycin selection." (PMID 38528605, 2024).
LGL leukemia (1 paper, 2022). "No.....e remission rates induced with demethylating agents in cases of TET2 mutated angioimmunoblastic lymphoma should prompt an assessment of their efficacy in LGL leukemia bearing the TET2 mutation." (PMID 35178350, 2022).
liver disease (1 paper, 2022). "Another experimental model using Tet2ΔDVAV mice, which are deficient in the epigenetic regulator Tet methylcytosine dioxygenase 2 (TET2), shows a key role of microbiome and cytotoxic T lymphocytes in inducing a liver disease closely resembling AIH." (PMID 36059527, 2022).
liver inflammation (1 paper, 2023). "Similarly, in dietary models of non-alcoholic steatohepatitis, mice transplanted with TET2-deficient hematopoietic cells demonstrated more severe liver inflammation and fibrosis due to elevated NLRP3 inflammasome and downstream inflammatory cytokine expression in TET2-deficient macrophages." (PMID 37928907, 2023).
Lymphatic Metastasis (1 paper, 2022). Transfer of a neoplasm from its primary site to lymph nodes or to distant parts of the body by way of the lymphatic system. "First, 17 genes were identified as clonal or private alterations in lymphatic metastasis; second, the alteration frequencies of TET2 (2% in P, 5% in LN) and ATR (3% in P, 8% in LN) were significantly higher in lymphatic metastasis than primary lesions, which considered as metastasis-related events." (PMID 35923575, 2022).
lysosomal storage disease (1 paper, 2022). A metabolic disorder caused by mutations in proteins critical for lysosomal function, including lysosomal enzymes, lysosomal integral membrane proteins, and proteins involved in the post-translational modification and trafficking of lysosomal proteins. "Thus, an extensive cross-talk between TET2 and the oncogenic transcription factor MYC establishes a lysosomal storage disease–like state that contributes to an exacerbated sensitivity to autophagy inducers." (PMID 35351824, 2022).
macrocytic anemia (1 paper, 2022). Anemia that is characterized by increased red blood cell volume. "Developing pancytopenia and particularly macrocytic anemia prompted the screening for a hematological malignancy, which led to the diagnosis of a TET-2-positive MDS." (PMID 35126364, 2022).
malignant pleural mesothelioma (1 paper, 2016). A malignant neoplasm that arises from mesothelial cells in the pleura and shows a diffuse growth pattern. "However, this decrease was significant in the rat for TET1 and TET3 between preneoplastic and neoplastic cell lines, and in humans for TET2 between normal mesothelial cells (MC) and malignant pleural mesothelioma cell lines (MPM)." (PMID 27129173, 2016).
metastatic cancer (1 paper, 2021). A carcinoma which has spread from the original site of growth to another anatomic site. "Intriguingly, in metastatic cancer cells of the MLN group, significant lower DNA 5hmC levels were detected, as well as lower TET1 and TET2 expression compared to those in the MT group." (PMID 33716151, 2021).
microphthalmia (1 paper, 2017). Congenital or developmental anomaly in which the eyeballs are abnormally small. "While the PLM and BrdU incorporation results suggest that elongation of the cell cycle during early retinal development underlies microphthalmia in tet2-/-;tet3-/- mutants, apoptosis of RPCs or newly differentiated neurons could also contribute." (PMID 28926578, 2017). "No increase in apoptotic cells was detected in tet2-/-;tet3-/- mutant until after 3dpf, indicating that apoptosis is unlikely to account for microphthalmia in tet2-/-;tet3-/- mutants." (PMID 28926578, 2017).
mucinous tumors (1 paper, 2012). "These include: FH, GMPS, PIK3CA, EIF4A2, ZNF384, and SS18L1 (amplifications in serous tumors); TET2, FGFR10P, NF1, ERBB2, and SH3GL1 (deletions in serous tumors) and ERBB2 (amplifications in mucinous tumors)." (PMID 23078675, 2012).
myocarditis (1 paper, 2025). Myocarditis is a condition that is characterized by inflammation of the heart muscle (myocardium). "In this study, using hiPSC-CMs as an in vitro infectious myocarditis model for SARS-CoV-2 infection, we found that endogenous TET2 expression and TET2-mediated m5C hydroxylation were significantly up-regulated as part of the epitranscriptomic modifications following SARS-CoV-2 infection." (PMID 40697650, 2025).
nutritional deficiency (1 paper, 2024). "Screening of CHIP-associated genes, particularly TET2, DNMT3A and ASXL1, can be an optional measure in CAR-T manufacturing in some elderly populations presenting CHIP bias, such as immune cytopenia, marrow dysplasia, and nutritional deficiency." (PMID 38191582, 2024).
osteosarcoma (1 paper, 2023). A usually aggressive malignant bone-forming mesenchymal neoplasm, predominantly affecting adolescents and young adults. "TET2-dependent protection from DNA damage-induced apoptosis has been described in the U-2 OS human osteosarcoma cell line." (PMID 37371754, 2023).
parathyroid tumor (1 paper, 2018). "In contrast to parathyroid tumor cells, TET2 is perhaps indispensable for SI-NET cells." (PMID 30045709, 2018).
pemphigus (1 paper, 2025). Pemphigus is a group of rare autoimmune diseases that cause blistering of the skin and mucous membranes (mouth, nose, throat, eyes, and genitals).This conditioncan occur at any age, but often strikes people in middle or older age. "Differential expression analysis was conducted to investigate the expression patterns of the five genes (XBP1, FBXO45, SAT2, AIFM1, and ACSL4) and eight other DEGs associated with ferroptosis (G3BP1, WBP11, TET2, IRF8, FASN, GDPD5, H1-4, and HUWE1) in both the pemphigus and control groups." (PMID 40612574, 2025).
peripheral artery disease (1 paper, 2023). "Compared to TET2 mutation carriers, patients with DNMT3A mutations had significantly less frequently concomitant coronary and peripheral artery disease." (PMID 36680616, 2023).
peritoneal mesothelioma (1 paper, 2022). A benign or malignant mesothelial neoplasm that arises from the peritoneum. "Here, we detected TET2 mutations in 4.2% of pleural mesothelioma samples and 2.5% of peritoneal mesothelioma patients." (PMID 36138075, 2022).
pituitary adenomas (1 paper, 2020). "In order to explore the pathogenesis of non-functioning pituitary adenomas (NFPAs), we detected genomic 5hmC levels in 57 NFPAs and 5 normal pituitary glands, and TET2 expression, distribution and TET2 alteration." (PMID 32774324, 2020).
pneumococcal infection (1 paper, 2024). Infections with bacteria of the species streptococcus pneumoniae. "In fact, when Quin and authors tested the role of Tet2 in pneumococcal infection, middle aged mice with Tet2 deleted from hematopoietic cells showed impaired bacterial clearance in the blood, enhanced systemic dissemination, and a reduction in overall survival following pulmonary challenge." (PMID 38828722, 2024).
primary hypertension (1 paper, 2022). "FGF5 has previously been implicated as a susceptibly region for primary hypertension, while TET2 has been implicated as an aldosterone responsive mediator of α epithelial sodium channel transcription (which has a role in BP regulation)." (PMID 35886043, 2022).
proliferative diabetic retinopathy (1 paper, 2024). Advanced retinopathy due to diabetes mellitus characterized by the formation of new vessels in the retina. "Here, we investigated the downstream genes of TET2 and its potential association with neovascularization in proliferative diabetic retinopathy (PDR)." (PMID 38172938, 2024).
scleroderma (1 paper, 2022). Scleroderma is a rare autoimmune connective tissue disorder characterized by abnormal hardening of the skin and, sometimes, other organs. "Since lower expression of TET2 in mononuclear cells was detected in >86% of inflammation‐associated PAH cases, our findings suggest higher TET2 expression in PAH patients with scleroderma was somewhat perplexing and surprising to us." (PMID 35581740, 2022).
seminoma (1 paper, 2013). A radiosensitive malignant germ cell tumor found in the testis (especially undescended), and extragonadal sites (anterior mediastinum and pineal gland). "Seminoma and EC cell lines and tumors display most prominent expression of TET1 while TET2 and TET3 are expressed at very low levels, suggesting that here TET1 is the main molecule involved in 5mC oxidation." (PMID 24386123, 2013).